PLK4 (polo like kinase 4)
Diseases named in the same sentence as PLK4 in open-access papers (continued):
Sharing a sentence is not in itself a finding about the gene and the disease.
keloid (2 papers, 2022 to 2025). An irregularly shaped, elevated mark on the skin caused by deposits of excessive amounts of collagen during wound healing. "Recent studies have also highlighted the role of PLK4 in other hyper-proliferative skin conditions such as keloids and psoriasis." (PMID 40940791, 2025). "In keloids, which are benign but aggressively growing fibroproliferative lesions, PLK4 is overexpressed relative to normal skin." (PMID 40940791, 2025). "We discovered that PLK4 was overexpressed in keloid dermal samples and KFs compared with adjacent normal skin samples and NFs derived from the same patients." (PMID 35670224, 2022). "Real‐time PCR analysis revealed that PLK4 mRNA expression in keloid dermal tissue was approximately 7.4‐fold higher than that in the adjacent normal skin dermis." (PMID 35670224, 2022). "In summary, we reported herein that keloids expressed high levels of PLK4, which induced tumor‐like malignant biological behaviors in KFs, including enhanced proliferation, migration, and invasion." (PMID 35670224, 2022). "PLK4 was overexpressed in keloid dermal samples and keloid fibroblasts (KFs) compared with adjacent normal skin samples and normal skin fibroblasts derived from the same patients." (PMID 35670224, 2022). "We confirmed that PLK4 expression was significantly elevated in keloid dermis samples compared to normal skin samples and that this upregulation was associated with the enhanced proliferation, migration, and invasion capacities of KFs." (PMID 35670224, 2022). "The expression of PLK4 was further explored in fibroblasts isolated from six pairs of keloid and adjacent normal skin dermal tissue samples." (PMID 35670224, 2022). "This study aimed to investigate the expression and biological role of PLK4 in the pathogenesis of keloids." (PMID 35670224, 2022). "In the present study, we investigated the expression patterns of PLK4 in keloids and normal skin and the role of PLK4 in apoptosis and cell cycle regulation in KFs for the first time." (PMID 35670224, 2022). "We first evaluated the expression of PLK4 in keloids and adjacent normal skin tissue samples from patients who were clinically diagnosed with keloids." (PMID 35670224, 2022). "Taken together, these results indicated that PLK4 expression is elevated in keloid dermal samples and KFs." (PMID 35670224, 2022). "The present study indicated for the first time that PLK4 is aberrantly upregulated in the dermal tissues of quasi‐neoplastic keloids." (PMID 35670224, 2022). "Furthermore, western blot analysis demonstrated that PLK4 protein expression in keloid dermal tissue was 5.4‐fold higher than that in the adjacent normal skin dermis." (PMID 35670224, 2022). "PLK4 was expressed in both keloids and normal skin epidermal tissue." (PMID 35670224, 2022). "Considering the tumor‐like characteristics of keloids, we hypothesized that PLK4 is overexpressed in KFs, which results in the uncontrolled growth and invasiveness of keloids via apoptosis and cell cycle regulation." (PMID 35670224, 2022). "In the present study, we found that keloids, which are considered dermal fibroproliferative tumors, exhibited higher mRNA and protein levels of PLK4 in the dermal layer, especially in the superficial dermis, than in their corresponding adjacent normal skin tissues." (PMID 35670224, 2022). "However, PLK4 expression was markedly elevated in the keloid dermis, especially the superficial dermis, compared with adjacent normal skin." (PMID 35670224, 2022). "Here, we discovered that PLK4 is a potential target for the treatment of keloids." (PMID 35670224, 2022). "We evaluated the expression of PLK4 in keloids and adjacent normal skin tissue samples." (PMID 35670224, 2022). "Then, we established PLK4 knockdown and overexpression cell lines in keloid fibroblasts (KFs) and normal skin fibroblasts (NFs), respectively, to investigate the roles of PLK4 in the regulation of proliferation, migration, invasion, apoptosis, and cell cycle in KFs." (PMID 35670224, 2022).
keloid (continued). "Thus, we speculated that PLK4 may also be involved in the aggressive behavior of keloids." (PMID 35670224, 2022). "To investigate the biological function of PLK4 in keloids, we used three lentivirus‐mediated short hairpin RNAs (shRNAs) and the negative control (NC) shRNA (shNC) to knockdown PLK4 expression in KFs." (PMID 35670224, 2022).
Lynch syndrome (2 papers, 2013 to 2024). An autosomal dominant hereditary neoplastic syndrome characterized by the development of colorectal carcinoma and a high risk of developing endometrial carcinoma, gastric carcinoma, ovarian carcinoma, renal pelvis carcinoma, and small intestinal carcinoma. "Moreover, the screening for Lynch syndrome, a risk factor for EC occurrence, was not performed in the current study, and therefore, the association of PLK4 with Lynch syndrome in EC patients who underwent surgical resection could not be determined." (PMID 38326803, 2024). "Lynch syndrome tumors showed up-regulation of 1129 genes, e.g. genes involved in G1/S transition (CCNE, CCNH, E2F2 and CDK2), DNA replication (CDC45, RPA1, RFC5, MCM4 and POLD3) and chromosomal organization and mitosis (CCNB2, MLF1IP, CASC5, KIF2C and PLK4), which is in line with previous findings." (PMID 23951239, 2013).
myelodysplastic syndrome (2 papers, 2020 to 2022). A clonal hematopoietic disorder characterized by dysplasia and ineffective hematopoiesis in one or more of the hematopoietic cell lines. "A Phase I trial of the oral PLK4 inhibitor CFI-400945 is currently recruiting patients with R/R AML or myelodysplastic syndrome (MDS) (NCT03187288)." (PMID 32536937, 2020). "But the expression of PLK4 was decreased in some hematologic malignancies compared to normal tissues, such as in 82.0% of lymphomas, 80.5% of myelodysplastic syndromes (MDS) and 60% of acute lymphoblastic leukemia (ALL) and did not display oncogene roles." (PMID 36051696, 2022).
primordial dwarfism (2 papers, 2017 to 2021). "Furthermore, the importance of PLK4 for proper cell proliferation and differentiation in humans is underpinned by recent studies demonstrating that mutations in PLK4 lead to primordial dwarfism and that abnormal gene amplification results in human embryos exhibiting aneuploidy." (PMID 27484406, 2017).
psoriasis (2 papers, 2022 to 2025). An autoimmune condition characterized by red, well-delineated plaques with silvery scales that are usually on the extensor surfaces and scalp. "In diseases like psoriasis and cSCC, IL-17-driven inflammation may synergize with PLK4-induced centriole duplication to enhance epidermal proliferation." (PMID 40940791, 2025). "Comparing PLK4 expression levels between psoriasis and normal skin, we found that PLK4 was significantly increased, suggesting that hyperplasia of the epidermis of skin might be linked with PLK4 overexpression." (PMID 36009523, 2022). "Analysis of original data of GSE109248 using OmicSoft platform (QIAGEN, Redwood City, CA, USA) demonstrated that unlike other PLK family members, the transcription level of PLK4 was relatively higher in psoriasis and lupus compared with normal control." (PMID 36009523, 2022).
rhabdoid tumor (2 papers, 2017 to 2025). An aggressive malignant embryonal neoplasm usually occurring during childhood. "We demonstrated initial evidence of PLK4 as a CNS druggable target for rhabdoid tumors and MB." (PMID 29340047, 2017).
adenoma (1 paper, 2020). A neoplasm arising from the epithelium. "Comparing of corresponding adenomas, the expressions of BUB1, BUB1B, PLK4, and DNA2 in carcinomas were higher." (PMID 33134313, 2020).
anaplastic large cell lymphoma (1 paper, 2015). Anaplastic large cell lymphoma (ALCL) is a rare and aggressive peripheral T-cell non-Hodgkin lymphoma, belonging to the group of CD30-positive lymphoproliferative disorders, which affects lymph nodes and extranodal sites. "Conversely, Plk4 transcription showed a downregulation pattern in the anaplastic lymphoma kinase-negative anaplastic large-cell lymphoma (Eckerle lymphoma data set), which showed a clear upregulation of KLF14 transcription." (PMID 26439168, 2015).
astrocytomas (1 paper, 2022). "According to the CGGA_693 and CGGA_325 datasets, the prognosis of patients with astrocytomas in the PLK4-high group was worse than that of patients in the PLK4-low group." (PMID 36620611, 2022). "The ROC curve showed that the expression level of PLK4 could distinguish between LGG (oligodendroglioma and astrocytoma) and HGG (gliomablastoma) in TCGA databases." (PMID 36620611, 2022).
atherosclerosis (1 paper, 2023). A disease characterized by the build-up of fatty material and calcium deposition in the arterial wall resulting in partial or complete occlusion of the arterial lumen. "In sum, our study has demonstrated that CFI-400945, an anticancer drug that inhibits PLK4, significantly blocks intimal hyperplasia of mouse carotid arteries but increases atherosclerosis in vivo and the underlying mechanism may involve the induction of SMC polyploidization and subsequent apoptosis." (PMID 36750553, 2023). "However, we think PLK4 inhibitor increased atherosclerosis at least partly by SMC polyploidization and apoptosis for the following two reasons." (PMID 36750553, 2023). "In this study, we demonstrated that CFI-400945, a selective inhibitor of PLK4, inhibited neointima formation of mouse carotid arteries resulting from complete carotid ligation but accelerated partial carotid ligation-induced atherosclerosis in ApoE−/− mice fed a high-fat diet." (PMID 36750553, 2023).
B cell lymphomas (1 paper, 2023). "We screened a panel of 32 B cell lymphoma cell lines for sensitivity to the PLK4 inhibitor CFI-400945." (PMID 36934096, 2023). "PLK4 is highly expressed in many cancers, including B cell lymphomas, but also expressed in normal cells, and its expression alone does not appear to indicate a functional requirement." (PMID 36934096, 2023).
breast ductal carcinomas (1 paper, 2015). "Results showed that there were significantly lower protein levels of KLF14, but higher levels of Plk4, in cancer tissues of breast ductal carcinomas as compared with the adjacent normal tissues." (PMID 26439168, 2015).
ciliopathy (1 paper, 2019). A genetic disorder of the cellular cilia or the cilia anchoring structures, the basal bodies, or of ciliary function. "For most proteins, the trend reflected results from the WCP (i.e. PLK4 is up‐, whereas CEP63 and CEP57 down‐regulated) with the ciliopathy‐associated proteins CEP41 and CENPF being notable exceptions." (PMID 31304626, 2019).
epididymitis (1 paper, 2024). Inflammation of the epididymis. "Assessment of epididymitis cross sections indicated that there were very few spermatozoa detected for the Plk4 cKO, and those that were present appeared abnormal compared to the control." (PMID 38943004, 2024).
influenza infection (1 paper, 2013). "In addition, four of the six (HK2, NEK8, PANK4, PLK4) have also been identified important for influenza virus replication in other influenza-genome screens." (PMID 23805279, 2013). "Expression of PLK4 transcript and protein were significantly modulated by miR-34c inhibitor/mimic and these also had a significant impact on viral replication suggesting that PLK4 is an important miR-34c target during influenza replication." (PMID 23805279, 2013). "While miR-34b and let-7i inhibitor/mimic treatments had no substantial effects on PLK4 transcript and protein expression (data not shown), miR-34c mimic considerably up-regulated PLK4 transcript and protein expression, as well as influenza NP levels." (PMID 23805279, 2013).
malignant glioma (1 paper, 2019). A grade III or grade IV glioma arising from the central nervous system. "In malignant gliomas, elevated PLK4 levels were associated with poor prognosis and enhanced radio-resistance, while PLK4 knockdown significantly increased the radio-sensitivity of GBM cells." (PMID 31035417, 2019).
non-melanoma skin carcinoma (1 paper, 2025). "Recent findings from our lab substantiate the oncogenic role of PLK4 in non-melanoma skin cancer." (PMID 40940791, 2025).
oligodendroglioma (1 paper, 2022). A well-differentiated (WHO grade II), diffusely infiltrating neuroglial tumor, typically located in the cerebral hemispheres. "The TCGA and CGGA_693 datasets showed that the prognosis of patients with oligodendroglioma with PLK4-high levels was worse than that of patients with PLK4-low levels." (PMID 36620611, 2022).
pancreatic ductal adenocarcinoma (1 paper, 2025). An infiltrating adenocarcinoma that arises from the epithelial cells of the pancreas. "High levels of PLK4 expression are associated with poor overall survival in pancreatic ductal adenocarcinoma patients." (PMID 41092110, 2025).
Primary microcephaly (1 paper, 2022). Head circumference below 2 standard deviations below the mean for age and gender at birth. "In man, homozygous mutations in PLK4 lead to primary microcephaly, altered PLK4 expression is associated with aneuploidy in human embryos." (PMID 35536377, 2022).
sarcoma (1 paper, 2015). A usually aggressive malignant neoplasm of the soft tissue or bone. "It will be important in future studies to identify the origins of these tumour cells, particularly the sarcomas that appear with increased frequency when Plk4 levels are elevated." (PMID 26701933, 2015). "However, a wide variety of sarcomas arose more frequently and earlier after Plk4 over-expression." (PMID 26701933, 2015).
uterine cancer (1 paper, 2025). Primary or metastatic malignant neoplasm involving the uterine corpus and/or the cervix. "Recent studies have shown the association of PLK4 with endometrial and uterine cancers." (PMID 41488365, 2025). "The PLK4 inhibitor CFI-400945 demonstrated significant antitumor activity in SK-UT-1, SKN, and SK-LMS-1 and SK-UT-1 cell lines and uterine cancer xenografts." (PMID 41488365, 2025).
uterine sarcomas (1 paper, 2023). "Polo-like kinase 4 (PLK4), Secreted Protein, Acidic and Rich in Cysteine (SPARC) Related Modular Calcium Binding 2 (SMOC2), Special AT-rich Sequence-Binding protein 2 (SATB2), or Forkhead box P3 (FOXP3) + T cells have all been suggested as prognostic indicators for uterine sarcomas." (PMID 37173887, 2023).
cancer (116 papers, 2012 to 2026). A tumor composed of atypical neoplastic, often pleomorphic cells that invade other tissues. "It was recently shown that inhibition of polo-like kinase 4 (PLK4) induces synthetic lethality in cancers with chromosome 17q-encoded TRIM37 copy number gain due to cooperative regulation of centriole duplication and mitotic spindle nucleation." (PMID 42288516, 2026). "Excessive PLK4 activity can result in centriole overduplication, disrupting normal centrosome function and contributing to genomic instability—a hallmark of cancer." (PMID 40710347, 2025). "Here, we have briefly discussed the structure and function of PLK4, its association in various cancers and its mechanisms." (PMID 41488365, 2025). "PLK4 has been reported to be overexpressed in various human cancers, where increased PLK4 expression is associated with worse clinicopathologic factors and poorer patient outcomes." (PMID 41092110, 2025). "This review highlights key concepts of PLK4‐mediated centriole duplication and emphasizes the underlying mechanisms of cancer‐specific susceptibility to PLK4 inhibition." (PMID 40257113, 2025). "The precise mechanism driving permanent cilium loss in cancers likely involves multiple factors, with PLK4 being a potential key player." (PMID 41488365, 2025). "Some studies have shown that lower levels of PLK4 were associated with faster tumor growth, advanced cancer stage, and poor patient survival." (PMID 41488365, 2025). "Aberrant PLK4 expression has been shown to be frequently associated with tumorigenesis, making it an attractive candidate for targeted cancer therapy." (PMID 41488365, 2025). "Below, we have focused on studies showing the association of PLK4 with cancers in vitro and in vivo." (PMID 41488365, 2025). "Studies have shown an association between PLK4 overexpression and cancer progression, metastasis, resistance to chemotherapy, and overall poor patient survival." (PMID 41488365, 2025). "Nonetheless, the extent to which PLK4 overexpression influences primary cilia loss or rescue in cancer remains undetermined." (PMID 41488365, 2025). "In the following sections, we summarize the latest research on PLK4 inhibition‐induced acentrosomal cell division and the associated cancer‐specific vulnerabilities." (PMID 40257113, 2025). "In this regard, given that aneuploidy is considered a cause of cancer development, our discovery of a ternary Vpr•VprBP•Plk4 complex and the ability of the complex to potentiate Plk4-mediated centriole duplication and induce aneuploidy are significant." (PMID 38443376, 2024). "Previous studies showed that PLK4 inhibition causes synthetic lethality in cancer cells with genomic amplification or overexpression of the centrosomal ubiquitin ligase TRIM37 which is a negative regulator of PCM59–62." (PMID 38951519, 2024). "Inhibition of PLK4 dysregulates centriole duplication and induces genomic instability and aneuploidy in cancer cells, causing antiproliferative effects and cell death." (PMID 38365710, 2024). "Centrosome amplification is a hallmark of cancer and PLK4 is one of the responsible factors for cancer associated centrosome amplification." (PMID 38388511, 2024). "Polo-like kinase 4 (PLK4) is associated with tumorigenesis and prognosis in various types of cancer." (PMID 37760631, 2023). "Dysregulation of Plk4 has been found in several types of cancers and shown to cause loss of centrosome numerical integrity, promoting genomic instability." (PMID 36797240, 2023).